LY6G6E (lymphocyte antigen 6 family member G6E (pseudogene))
Synonyms: LY6G6EP; G6e; formerly C6orf22
Gene: Transcribed unitary pseudogene on chromosome 6 (31,712,341 to 31,713,812, reverse strand). Ensembl gene ENSG00000255552.
Diseases named in the same sentence as LY6G6E in open-access papers:
LY6G6E is named in the same sentence as 2 diseases in open-access papers, as found by Europe PMC text mining. Sharing a sentence is not in itself a finding about the gene and the disease. The quoted sentences say what the papers report.
neurological diseases (1 paper, 2019). "Among these genes, Ch25h, Trpa1, Cdkn1a, Ly6g6e, Six3, and Opalin are potentially associated with neurological diseases; Lcn2, Serpina3f, Lao1, Trim29, bcl3, and Gkn3 are associated with inflammatory response." (PMID 30804943, 2019).
LY6G6E also shares sentences with these, for which no sentence is quoted: lung carcinoma (1 paper).